CXCR4 (C-X-C motif chemokine receptor 4)
Diseases named in the same sentence as CXCR4 in open-access papers (continued):
Sharing a sentence is not in itself a finding about the gene and the disease.
HIV-1 infection (continued). "In surprising contrast, not only did alkyl-CIMSS fail to inhibit HIV-1 infection, but it significantly increased both HIV-1BaL (R5-utilizing strain) and HIV-1IIIB (CXCR4-utilizing strain) infection of TZM-bl cells in a dose dependent manner relative to cells treated with DMSO control." (PMID 41278678, 2025). "In a humanized mouse model, CRISPR/Cas9-mediated reduction significantly decreased the surface expression of the CCR5 and CXCR4 co-receptors in primary CD4 + T cells, thereby establishing protection of the cells from HIV-1 infection by R5-tropic, X4-tropic, and dual R5/X4-tropic strains." (PMID 38741006, 2024). "So far, a drug directly targeting the CXCR4 co-receptor for the treatment of HIV-1 infection is not yet available clinically." (PMID 38131305, 2023). "During HIV-1 infection, WKYMVm desensitizes HIV-1 coreceptors C-C motif chemokine receptor 5 (CCR5) and C-X-C motif chemokine receptor 4 (CXCR4) on the surface of monocytes by activating FPR2, thereby effectively inhibiting HIV-1 Env-mediated fusion and viral infection." (PMID 36120322, 2022). "As such, we targeted the expression of five genes with roles in HIV-1 infection (CD4, CXCR4, PSGL-1, TRIM5α and CPSF6) as well as CD46, in part using gRNAs pre-tested for each target for the efficiency of editing and protein loss was assessed in part by confocal microscopy." (PMID 34949807, 2022). "Fourth, GPI-10E8 and its bifunctional derivatives (CMI02 and CMI06) were highly effective in transduced human CEMss-CCR5 cells to inhibit both CCR5- and CXCR4-tropic HIV-1 isolates and the modified cells experienced a robust survival selection under HIV-1 infection." (PMID 34821542, 2022). "CCL-19 neither elicits T cell activation nor induces CCR5 or CXCR4 expression, but enhances cis HIV-1 infection of resting CD4+ T cells." (PMID 33688006, 2021). "In agreement with this assumption are previous studies reporting that MSX-122 is not preventing CXCL12 binding, and our data presented here that MSX-122 is not affecting CXCR4-tropic HIV-1 infection, in contrast to most other tested CXCR4 antagonists." (PMID 32994431, 2020). "The significance of CXCR4 in HIV-1 infection is not necessarily limited to its function as an HIV-1 coreceptor." (PMID 32154191, 2020). "Indeed, previous researches had shown that disruption of co-receptor CXCR4 and HIV-1 provirus by SaCas9/gRNAs promoted human primary CD4+ T cells and Jurkat T cells resistance to HIV-1 infection." (PMID 31186067, 2019). "The CXCL12/CXCR4/ACKR3 axis plays key roles in many physiological and pathological processes, including embryogenesis, wound healing processes, angiogenesis, in the development and metastasis of tumors and during HIV-1 infection." (PMID 31507535, 2019). "Similarly, CD34−CD7−CXCR4+ cells exhibited the greatest growth impairment following HIV-1 infection, as compared to CD34−CXCR4+ and CD34−CD7+CXCR4+ cells." (PMID 30761146, 2019). "Inhibitors of CHEK2, CSNK2A1, and CDK2 did not significantly reduce CCR5-tropic HIV-1 infection but inhibited CXCR4-tropic HIV-1 at one or more concentrations." (PMID 29970186, 2018). "In addition, simultaneous knockout of CXCR4 and CCR5, using one CXCR4/CCR5 combination sgRNA and CRISPR-SpCas9, was assessed in primary CD4+ T cells and showed an inhibition of dual tropic HIV-1 infection." (PMID 29337866, 2018). "These discoveries prompted us to find a way to replace wild-type CXCR4 with the CXCR4 (P191A) mutant, to confer resistance against HIV-1 infection without affecting normal immune functions in HSC development." (PMID 29872154, 2018). "ITK is not expressed in HEK293T or HeLa cells; however, if these cells are genetically modified to express CD4 and CXCR4, they are fully permissive for HIV-1 infection (data not shown)." (PMID 29453458, 2018).
HIV-1 infection (continued). "The TZM-bl cells are of epithelial origin, and the acute T cell leukemia (ATCL) derived Jurkat T cells, like primary human CD4+ T cells, are suspension cells with expression of co-receptor CXCR4 and CCR5 on cell surface, which can be a perfect option for HIV-1 infection study." (PMID 28904745, 2017). "However, to date, only one study has investigated simultaneous CXCR4 and CCR5 modification using CRISPR-Cas9, which was reported to inhibit HIV-1 infection in cells." (PMID 28904745, 2017). "Importantly, the modified cells are resistant to CXCR4-tropic or/and CCR5-tropic HIV-1 infection and exhibit a selective advantage over unmodified cells throughout the HIV-1 infection period." (PMID 28904745, 2017). "We then tested whether the disruption of CXCR4 and CCR5 on primary CD4+ T cells protected cells from HIV-1 infection." (PMID 28904745, 2017). "We next examined whether simultaneous knockout of CXCR4 and CCR5 in Jurkat T cells rendered the modified cells resistant to HIV-1 infection." (PMID 28904745, 2017). "However, the effects of simultaneous genome editing of CXCR4 and CCR5 by CRISPR-Cas9 in blocking HIV-1 infection in primary CD4+ T cells has been rarely reported." (PMID 28904745, 2017). "We next examined whether lenti-X4R5-Cas9-#1 and lenti-X4R5-Cas9-#2 mediated CXCR4 and CCR5 disruption could protect TZM-bl cells from HIV-1 infection." (PMID 28904745, 2017). "These double co-receptor negative cells were resistant to both CCR5- and CXCR4-tropic HIV-1 infection in a humanized mouse model, suggesting that this strategy is a reasonable approach in HIV-1 functional cure." (PMID 26588898, 2015). "Because CCR5, CXCR4 and CD4 expression or differences in cell growth could affect HIV-1 infection, we compared CXCR4 and CD4 expression and cell growth of CCR5-/CR1, CCR5-/CR2 and CCR5-/CR3 cells with those of mock-transduced TZM.bl cells." (PMID 25541967, 2014). "XCL1 potently inhibited HIV-1 infection irrespective of coreceptor specificity, as it was equally effective on strains specific for CXCR4 (X4; IIIB) and CCR5 (R5; BaL)." (PMID 24385911, 2013). "We examined the impact of HIV-1 infection on production of CCR5+ and CXCR4+ CD4T in MDM cultures." (PMID 22911696, 2012). "Mutation of Asn11 does not impair the CXCR4-mediated HIV-1 infection; however, a Asn11-to-Glu11 mutation leads to enhanced binding of both CXCR4-specific and dual-tropic (CCR5 and CXCR4) HIV-1 isolates." (PMID 21284899, 2011). "Among other soluble factors it secretes chemokines, in particular stromal-derived factor 1 (SDF-1), the natural ligand for CXCR4 that in vitro selectively suppresses X4 HIV-1 but not R5 HIV-1 infection." (PMID 21284905, 2011). "It is well established that HIV-1 infection typically involves an interaction between the viral envelope protein gp120/41 and the CD4 molecule followed by a second interaction with a chemokine receptor, usually CCR5 or CXCR4." (PMID 21284901, 2011). "Moreover, CXCR4 in the proteoliposomes binds CXCL12, the natural ligand, and AMD3100, a small-molecule inhibitor of HIV-1 infection." (PMID 20967243, 2010). "Despite the presence of the CD4 molecule as well as CCR5 and CXCR4, no cell-free HIV-1 infection was detected in this cell line." (PMID 19445667, 2009). "Coreceptors other than CCR5 and CXCR4, that are related to the clinical involvement of the HIV-1 infection have not yet been clarified." (PMID 18577234, 2008). "In addition to anti-HIV genes with a direct inhibitory action on viral molecules, siRNAs and ribozymes that down regulate cellular molecules that aid in HIV-1 infection such as viral coreceptors CCR5 and CXCR4 also show considerable promise." (PMID 18215326, 2008). "Although humans carrying a 32–base pair deletion of the CCR5 gene are resistant to HIV-1 infection, no R5 virus has yet been isolated that overcomes this inhibitory effect; infection is only possible via T-tropic virus that uses the CXCR4 coreceptor." (PMID 17397262, 2007).
HIV-1 infection (continued). "In addition, a number of cellular molecules that aid in HIV-1 infection such as cellular receptors and coreceptors CD4, CCR5 and CXCR4 have also been successfully tested in CD34 cell derived macrophages and T cells." (PMID 16623949, 2006). "The surface markers analyzed were CD14, a monocyte/macrophage specific marker, HLA-DR (a class II MHC molecule found on antigen presenting cells), CD4, the major receptor for HIV-1 infection, and CCR5 and CXCR4, chemokine receptors which are critical coreceptors essential for HIV-1 entry." (PMID 16623949, 2006). "Thus, the bispecific lentiviral vector harboring both CXCR4 and CCR5 shRNAs, described here, would be ideal in preventing HIV-1 infection at the cell entry stage." (PMID 16109172, 2005). "Therefore, we recently demonstrated that synthetic bispecific combinatorial constructs as well as a bispecific lentiviral vector targeting both CXCR4 and CCR5 showed efficacy in inhibiting HIV-1 infections in cell culture lines." (PMID 16109172, 2005). "In HIV-1 infection, FPR2 on the one hand may inhibit viral infection through HIV-1 co-receptor CCR5 and CXCR4 cross-desensitization mediated by activation through glycoprotein fragments, but on the other hand can act as a co-receptor for HIV-1 viral entry itself." (PMID 40703440, 2025). "Furthermore, TIQ-15 did not inhibit VSV-G pseudotyped HIV-1 infection, demonstrating its specificity in blocking CXCR4-tropic virus entry, but not CXCR4-independent endocytosis or post-entry steps." (PMID 39146384, 2024). "However, other studies argue that during the early stages of HIV-1 infection, characterized by cytokine storm, IL–18 might suppress HIV-1 by increasing the T lymphocytes’ type 1 (Th1) immune response and reducing CXCR4 co-receptor expression." (PMID 37937297, 2023). "To elucidate CD4CAR mediated HIV-1 infection, we transduced HOS.CCR5 or HOS.CXCR4 cells that are not susceptible to HIV-1 due to the lack of CD4 expression with lentiviral vectors expressing the CD4CAR or D1D2CAR and then infected them with either R5 tropic HIVNFNSXSL9 or X4 tropic HIVNL4-3." (PMID 33793675, 2021). "Results showed that CXCR4 and CCR5 knockout (KO) cell were resistant to HIV-1 infection in a tropism-dependent manner whereas TRN-SR2 and LEDGF KO cells led to a reduced infection independent of tropism confirming the vital role of these cofactors in HIV-1 infection." (PMID 34064404, 2021). "This may be because the transfection efficiencies (35 to 40%) were higher than HIV-1 infection rates (10 to 15%) in CD4/CXCR4/CCR5 cells (data not shown)." (PMID 32127461, 2020). "A previous report showed that the natural CXCR4 P191A mutant inhibits HIV-1 infection without any defect in HSC differentiation, which could provide a basis for the development of new approaches for HIV-1 gene therapy." (PMID 29872154, 2018). "These genome-edited cells have a selective advantage during CCR5-tropic or/and CXCR4-tropic HIV-1 infection and the lenti-X4R5-Cas9 vectors did not have non-specific cleavage or cytotoxicity after both CXCR4 and CCR5 disruption, which showed a specific targeting of HIV-1 receptors." (PMID 29337866, 2018). "As expected, expression of HAFv1n in U87MG CD4/CXCR4 cells did not inhibit HIV-1 infection." (PMID 28747499, 2017). "Moreover, AAT also did not directly interact with CD4, CCR5, CXCR4 and other HIV-1 infection-related proteins." (PMID 27473095, 2016). "It is highly vulnerable to HIV-1 infection, related to the subjacent lamina propria which, in health, is densely populated with activated memory T-cells expressing both CD4 and both HIV-1 co-receptors CCR5 and CXCR4, as well as dendritic cells (DCs) and macrophages." (PMID 21969851, 2011). "In addition, since A120 mAb treatment increases CXCR4 expression on CD4+ T cells, it may also be possible that the A120 mAb may block X4 HIV-1 infection by interfering with CXCR4 trafficking." (PMID 22018245, 2011).
HIV-1 infection (continued). "However, despite a functional CD4 receptor and the endogenously expressed CCR5 and CXCR4 co-receptors, cell-free HIV-1 infection was still restricted in BeWo-CD4+ cells (data not shown)." (PMID 19445667, 2009). "However, prior studies have suggested that although CCR5 coreceptors are down-modulated during infection by R5 HIV-1, CXCR4 co-receptor is not down-regulated after productive X4 HIV-1 infection." (PMID 18190699, 2008). "Importantly, for moving forward in evaluating whether modified B cells could provide sufficient eCD4-Ig-KiHR in vivo to control HIV-1 infection, culture supernatants demonstrated robust anti-HIV-1 activity against three HIV-1 isolates of both CXCR4 and CCR5 tropisms." (PMID 36879849, 2023). "Our results showed that BMS-986158 moderately down-regulated the expression of the CXCR4 and CCR5 co-receptors in the CD4+ T cells, indicating that BMS-986158 does not increase potential de novo HIV-1 infection." (PMID 35337136, 2022). "IL-21 inhibited both R5- and X4-tropic HIV-1 infection, and did not alter surface expression of the HIV entry coreceptors CD4, CCR5 or CXCR4 on CD4 T cells, suggesting that the antiviral mechanism of IL-21 likely involved post-entry events." (PMID 26108174, 2015). "The changes observed in the abundance of CCR5 and CXCR4 chemokine receptors on CD4+ T-cells and of cytokines/chemokines during the natural course of non-clade B HIV-1 infection suggests that the phenotypic switch is not driven by changes in the levels of these receptors or anti-HIV cytokines." (PMID 21655330, 2011). "One possible explanation is that a small fraction of CD4 and CXCR4 on PBMCs, but not on MT4 cells, are sufficient for HIV-1 infection; as a result, partial down regulation of CD4 and CXCR4 potently inhibits HIV-1 infection of MT4 cells but is not effective against ×4 virus infection of PBMCs." (PMID 22039528, 2011). "Moreover, we demonstrated that GPI-m36.4 could efficiently render human CD4+ T cells (CEMss-CCR5) nonpermissive to both CCR5- and CXCR4-tropic HIV-1 isolates and produced a robust survival advantage in transduced cells compared to unmodified cells during HIV-1 infection." (PMID 33462383, 2021).
colorectal cancer (207 papers, 2006 to 2026). A primary or metastatic malignant neoplasm that affects the colon or rectum. "At the current level of evidence, this study demonstrates that CXCR4 overexpression in patients with colorectal cancer is associated with a significantly diminished overall as well as disease-free survival." (PMID 38791414, 2024). "For example, CXCR4 expression in primary tumor cells is associated with recurrence, metastasis, and survival in colorectal cancer." (PMID 37378300, 2023). "CXCR4, a member of the C-X-C chemokine receptor family, is associated with a variety of cancers, and high CXCR4 expression in esophageal, gastric, and colorectal cancers predicts poor prognosis." (PMID 36642706, 2023). "Recent studies have reported that RAS-ERK1/2 signaling induces the upregulation of Ang2 and c-x-c motif chemokine receptor 4 (CXCR4) in KRAS-mutated colorectal cancer cells, resulting in liver metastasis." (PMID 35874764, 2022). "C-X-C motif chemokine receptor 7 (CXCR7) is a newly discovered atypical chemokine receptor that binds to C-X-C motif chemokine ligand 12 (CXCL12) with higher affinity than CXCR4 and is associated with the metastasis of colorectal cancer (CRC)." (PMID 35443745, 2022). "Biparatopic nanoparticles promote a highly selective tumor destruction in a mouse model of human colorectal cancer, probably associated to the CXCR4 antagonist role of EPI-X4." (PMID 34208189, 2021). "The new peptide CXCR4 antagonist, Pep R, was associated with standard chemotherapy in colorectal cancer." (PMID 32708431, 2020). "Subgroup analysis also indicated that high CXCR4 expression in esophagus, gastric, and colorectal cancers was associated a worse prognosis." (PMID 32260318, 2020). "The other studies have shown that the expressions of CXCL12 and CXCR4 in colon cancer patients are associated with liver metastasis, recurrence rate and survival rate in colorectal cancer patients." (PMID 29305742, 2018). "Statistical analysis showed that high CD133+CXCR4+ cell content is associated with poor 2-year survival of colorectal cancer patients." (PMID 22871210, 2012). "Clinical studies haveshown that although VEGF and CXCR4 both predispose to lymphatic involvement andnodal metastasis in colorectal cancer, they work through different regulatorystrategies." (PMID 18779872, 2008). "Moreover, exosomal transfer of miRNA from CXCR4-overexpressing colorectal cancer cells to tumor-associated macrophages was shown to enhance their M2 polarization and metastasis-promoting characteristics." (PMID 36725964, 2023). "Tranfection of CXCR4 siRNA led to a near total loss of CXCR4 expression of colorectal cancer cells." (PMID 34930323, 2021). "Taken together our preclinical results show that a newly developed CXCR4 antagonist Pep R is able to improve standard therapy efficacy targeting cell growth and mesenchymal transition, endorsing further clinical studies for association of CXCR4 antagonists plus standard therapy in colorectal cancer." (PMID 32708431, 2020). "CXCR4 is overexpressed in colorectal cancer cells and linked to tumor aggressiveness." (PMID 27059706, 2016). "Furthermore,elevated CXCR4 expression in colorectal cancer is associated with diseaseprogression and reduced survival." (PMID 18779872, 2008). "Some of them include miR-146, which has shown to supress cell proliferation in colorectal cancer cells (CRC) by downregulating CXCR4." (PMID 40307933, 2025). "In colorectal cancer, the CXCR4/CXCL12 axis plays a role in tumor development, invasion, angiogenesis, and metastasis." (PMID 40006069, 2025). "C-X-C Chemokine receptor type 4 (CXCR4) is the most frequently expressed chemokine receptor across more than 23 types of human cancers, including colorectal cancer." (PMID 40006069, 2025). "In the present systematic review and meta-analysis, tumoral overexpression of the chemokine receptor CXCR4 serves as a significant biomarker of poor prognosis in colorectal cancer patients." (PMID 38791414, 2024).